KCNQ2 (potassium voltage-gated channel subfamily Q member 2)
Diseases named in the same sentence as KCNQ2 in open-access papers (continued):
Sharing a sentence is not in itself a finding about the gene and the disease.
genetic disorders (4 papers, 2016 to 2022). "In some genetic disorders, especially KCNQ2 and KCNA2, there was always the first stage of different EEG patterns preceding ESES." (PMID 33897753, 2021). "Recently, ESES had been reported in some genetic disorders, such as KCNQ2, ZEB2, and SLC9A6." (PMID 33897753, 2021).
movement disorder (4 papers, 2022 to 2025). Neurological conditions resulting in abnormal voluntary or involuntary movement, which may impact the speed, fluency, quality and ease of movement. "However, reports of KCNQ2-associated movement disorder are rare." (PMID 35269516, 2022).
tumor (3 papers, 2022 to 2025). "Metastatic tumor cells clustered with adrenergic cells and showed high expression of adrenergic signature genes PHOX2B, MDK, and KCNQ2." (PMID 38358826, 2024). "Tumor cells were characterized by high expression of NB tumor signature genes (PHOX2B, HAND2, STMN2, and KCNQ2), which were exclusively expressed in the BM of metastatic patients with NB." (PMID 38358826, 2024). "Our study provides compelling evidence that KCNQ3 is significantly upregulated in PTC tissues, driving tumor cell proliferation, migration, and progression through mechanisms independent of KCNQ2." (PMID 41250218, 2025).
cancer (2 papers, 2018 to 2023). A tumor composed of atypical neoplastic, often pleomorphic cells that invade other tissues. "Both genes are in chromosomal regions commonly amplified in GI cancers (KCNQ2: chromosome 20q13.3; KCNQ3: chromosome 8q24.22) and known to be involved in cancer progression." (PMID 37748809, 2023). "A total of 43 genes reside within 10 kb of these regions (column B), including those involved in cancer pathways (e.g. MMP2), angiogenesis (e.g. VEGFA), hypoxia response (e.g. SCAP), and neural development (e.g. KCNQ2), with downregulation of these loci being the dominant transcriptional effect." (PMID 29587824, 2018).
infection (2 papers, 2019 to 2024). The state of being infected such as from the introduction of a foreign agent such as serum, vaccine, antigenic substance or organism. "KCNQ-type K+ channels composed of KCNQ2 and KCNQ4 may play a role in intestinal secretion and defense mechanisms in the case of infection and loss of epithelial integrity." (PMID 30250967, 2019).
KCNQ2 also shares sentences with these, for which no sentence is quoted: long QT syndrome (4 papers); Anxiety (3); breast carcinoma (3); developmental disabilities (3); Alzheimer disease (2); Angelman syndrome (2); Arrhythmia (2); Benign familial neonatal-infantile seizures (2); bone cancer (2); cardiovascular diseases (2); episodic ataxia (2); episodic ataxia type 1 (2); Hypertension (2); Hypsarrhythmia (2); injury (2); microcephaly (2); Myoclonus (2); neurodegenerative disease (2); Neurodevelopmental delay (2); neuropathy (2); psychiatric disorder (2); Rolandic epilepsy (2); Acute encephalopathy (1); Aphasia (1); Arthritis (1); atrial fibrillation (1); Autoimmunity (1); bladder cancer (1); brain disorder (1); brain injury (1).
A further 48 diseases each share a sentence with KCNQ2 in 1 paper.